IL6 (interleukin 6)
Diseases named in the same sentence as IL6 in open-access papers (continued):
Sharing a sentence is not in itself a finding about the gene and the disease.
periodontitis (continued). "Furthermore, plasma leptin concentrations in periodontitis patients have been shown to correlate with pro-inflammatory cytokines implicated in disease pathogenesis, such as interleukin (IL)-1, IL-6, and tumour necrosis factor-alpha (TNF-α)." (PMID 41154857, 2025). "Additionally, research has shown that IL-6 is linked to the release and activation of Matrix metalloproteinases (MMPs), which can lead to pathological extracellular matrix degradation in periodontitis patients." (PMID 39251207, 2025). "Human gingival fibroblasts have been identified as important players in the host response to P. gingivalis, participating in interactions with the bacteria and producing inflammatory cytokines such as IL-1β and IL-6, which have been linked to the pathogenesis of periodontitis." (PMID 39699191, 2025). "The -174G/C and -572C/G IL-6 gene polymorphisms increase IL-6 expression, so they may be associated with susceptibility to periodontitis." (PMID 38396821, 2024). "IL-6, IL-17, and IL-35 levels were associated with periodontitis (odds ratio [OR] = 1.344, 95% confidence interval [CI] = 1.159–1.56; OR = 1.063, 95% CI = 1.025–1.102; OR = 1.261, 95% CI = 1.110–1.434, respectively) (p < 0.001, p = 0.001, p < 0.001, respectively)." (PMID 39215253, 2024). "Previous research data has demonstrated that periodontitis has been linked with increased systemic levels of cytokines, such as interleukin-1α,1β, interleukin-6 (IL-6), C-reactive protein (CRP), TNF tumor necrosis factor-α and interferon-γ in serum or plasma of periodontal compromised individuals." (PMID 39413077, 2024). "Additionally, it was found that the levels of salivary IL-6 are significantly induced in patients with calculus associated chronic periodontitis as compared to healthy control subjects and cytokine levels were correlated to disease progression." (PMID 39253090, 2024). "Moreover, IL-6, IL-17, and IL-35 levels were associated with periodontitis (OR = 1.344, 95% CI = 1.159–1.56; OR = 1.063, 95% CI = 1.025–1.102; OR = 1.261, 95% CI = 1.110–1.434, respectively) (p < 0.001, p = 0.001, p < 0.001, respectively)." (PMID 39215253, 2024). "IL-6 plays—as the current science reveals—a key role in PD, and single nucleotide IL-6 polymorphism mutations can aid in determining an increased risk of developing periodontitis." (PMID 38396821, 2024). "Likewise, the elevated levels of IL-6 in the GCF of pregnant patients with periodontitis were associated with a higher risk of subsequent development of preeclampsia." (PMID 37342498, 2023). "In a previous study of a periodontitis model, there was increased gingival expression of inflammatory mediators, including molecules that are implicated in bone resorption such as interleukin (IL)-6, TNF, and IFN-γ." (PMID 38029238, 2023). "The associations between IL-6 polymorphisms and periodontitis have been extensively studied." (PMID 37239434, 2023). "This increase in IL-6 is strongly correlated with the presence of C-reactive protein and may be closely linked to oral parameters of patients with periodontitis, such as increased probing pocket depth and number of teeth." (PMID 37026605, 2023). "Genetically proxied IL-6 signaling downregulation was associated with a reduced odds of periodontitis (OR per 1-unit decrement in log-CRP levels = 0.81; 95% confidence interval (CI): [0.66; 0.99]; P = 0.0497) in the inverse variance weighted (multiplicative random effects) regression." (PMID 37342352, 2023). "Periodontitis is associated with increased IL-6 and CRP levels." (PMID 37239434, 2023). "Elevated levels of IL-6 and IL-8 are often associated with periodontitis." (PMID 37894657, 2023). "The study focuses on the effects of IL-6 -572 C/G gene polymorphisms on chronic periodontitis in CAD, which remain unclear." (PMID 37239434, 2023). "Salivary IL-6 levels increased significantly with periodontitis severity and tooth loss." (PMID 36769328, 2023).
periodontitis (continued). "There is also an association between some IL-6 gene polymorphism and aggressive periodontitis." (PMID 37608339, 2023). "However, the periodontitis-associated TH17 cells proliferation requires of IL-6 and IL-23 to increase the production of IL-17A." (PMID 36967976, 2023). "When the secretion of IL-6 increases in some diseases associated with bone loss, such as periodontitis, peri-implantitis, and osteoporosis, binding of IL-6 to its receptor, IL-6R, promotes homodimerization of GP130, which then activates downstream signal transduction to cause bone resorption." (PMID 36643585, 2023). "OSA may increase the risk of developing periodontitis due to increase of IL-1β and IL-6 in saliva and IL-6, IL-17A and IL-33 in GCF that share the activation of the osteoclastogenesis." (PMID 36967976, 2023). "IL-6 -572 may be a genetic risk factor for periodontitis patients in Asian populations, especially the Chinese population." (PMID 37239434, 2023). "Because of its potent anti-inflammatory action, resveratrol is thought to slow the progression of PD, and some research has highlighted its important role in patients with type 2 diabetes and associated periodontitis, both in the restriction of serum IL6 levels and its ability to reduce glycemia." (PMID 37600299, 2023). "IL-6 rs1800796 may serve as one genetic risk factor for periodontitis patients in the Asian population, especially the Chinese population." (PMID 35454140, 2022). "In addition, the role of other inflammatory cytokines, including IL-4, IL-6, IL-10, IL-17, and IL-37, their polymorphisms, receptors, and signaling pathways are involved in the pathogenesis of periodontitis and the clinical severity of the disease." (PMID 36142220, 2022). "Furthermore, high expression levels of proinflammatory cytokines, including IL-6, were found in periodontitis and triggered osteoclast activity, which caused bone resorption." (PMID 35804048, 2022). "Periodontitis caused an increase in gingival levels of IL-6 and CXCL2 in the animal model." (PMID 34024010, 2022). "Gram-negative anaerobic bacteria, especially Porphyromonas gingivalis, are the main pathogenic bacteria of periodontitis, and their main pathogenic component, lipopolysaccharide, can induce bone destruction by triggering the release of proinflammatory mediators such as IL-6 and TNF-α." (PMID 35586136, 2022). "Previous studies suggested that IL-6 was associated with periodontitis." (PMID 35804048, 2022). "The IL-6 174G/C polymorphism increases the risk of developing periodontitis." (PMID 35628348, 2022). "Whether IL-6 mediates the aggravating effect of orthodontic forces on periodontitis-induced bone loss observed in the present study should be clarified in further inhibition experiments." (PMID 34024010, 2022). "Inflammatory factors such as tumor necrosis factor-α (TNF-α), interleukin-1β interleukin (IL)-1β, IL-6, and IL-17 play an important role in the pathology of chronic periodontitis because they cause secondary damage to periodontal tissues thereby exacerbating the destruction of periodontal tissues." (PMID 35942384, 2022). "Nonetheless, IL-6 and IL-10 polymorphisms are found to be potential risk factors for periodontitis." (PMID 35571048, 2022). "Moreover, the IL6 -174 “C” allele was protective against periodontitis in the Brazilian population in a recent meta-analysis." (PMID 35454140, 2022). "Hepcidin is upregulated by IL-6 and may have a role in systemic inflammation caused by periodontitis." (PMID 36414950, 2022). "In experiments on mice, inhibition of IL-6-influenced inflammation by blocking its receptor could reduce alveolar bone loss, supported by alterations in Th17 responses to periodontitis." (PMID 35628348, 2022). "Consequently, active periodontitis is associated with elevated salivary concentrations of pro-inflammatory mediators, including interleukin-1 beta (IL-1β), interleukin-6 (IL-6), interleukin-8 (IL-8), and tumor necrosis factor alpha (TNF-α)." (PMID 35048079, 2021).
periodontitis (continued). "In our study, the expression of inflammatory cytokines in OSCC showed that periodontitis-associated bacteria significantly (p < 0.05) upregulated IL-6, TNF-α, IL-18, ASC (up to six times), and caspase-1 (up to four times) but downregulated NF-κB, NLRP3, and IL-1β (less than 0.5 times)." (PMID 34660289, 2021). "On the other hand, prolonged and elevated secretion of IL-6 may induce periodontal bone loss in patients with chronic periodontitis by osteoclast activation caused by the overexpression of RANKL." (PMID 34029354, 2021). "This study also suggested that anti-IL-17A Abs decreased IL-6 gene expression in gingival tissue of periodontitis-induced mice and suppressed alveolar bone loss and osteoclastic activity; hence, IL-17A Abs might be an effective treatment for periodontitis." (PMID 34445604, 2021). "Periodontitis is one of the main causes of tooth loss and is able to increase the plasma concentrations of proinflammatory mediators such as IL-1, IL-6, and TNF-α, thereby contributing to worsening neuroinflammatory processes in the brain and ultimately resulting in cognitive impairment." (PMID 33514062, 2021). "Similarly, IL-6 −174G/C C allele model also had a weak relationship in the prevention of periodontitis development with OR (95% CI), 1.09 (0.81–1.36)." (PMID 35046930, 2021). "The results of qRT-PCR showed that the effect of LA may be linked to the progression of periodontitis because the expression of IL-6 was increased." (PMID 34832662, 2021). "Investigation of the IL-6 salivary level in patients with mild, moderate, and severe periodontitis in comparison to healthy controls, showed that IL-6 level proportionally increased with the severity of periodontitis, which suggests the potential diagnostic ability of IL-6." (PMID 33081038, 2020). "In this study, experimental periodontitis was associated with the progressive and increased presence of Th17 and Treg-related mediators in the gingiva (IL-6, IL-17A, IL-17F, RANKL, IL-10, TGF-β and GITR; P < 0.05), and the proliferation of both Treg and Th17 cells in cervical lymph nodes." (PMID 33149125, 2020). "The susceptibility to periodontitis seems to be increased with IL-6 gene 174/G>C polymorphism." (PMID 33081038, 2020). "Moreover, periodontitis has been positively associated with higher serum levels of different inflammatory biomarkers, such as interleukin 6 (IL-6), IL-17, C-reactive protein, and prostaglandins." (PMID 31817129, 2019). "The purpose of this study was to evaluate the effect of interleukin-10 (-597) gene polymorphism and genotype distributions on chronic periodontitis (CP) development and IL-6 and IL-10 levels in gingival crevicular fluid (GCF) and serum before and after non-surgical periodontal treatment." (PMID 29489938, 2018). "IL-6 -174G genotype has been found to be associated with Aggregatibacter actinomycetemcomitans in generalised aggressive periodontitis patients and with both Aggregatibacter actinomycetemcomitans and Porphyromonas gingivalis in IL-6 -174GG and IL-6 -6106AA polymorphisms." (PMID 29760828, 2018). "Our data demonstrated that Ruxolitinib significantly reduced the percentage of RORγt and IL-17 positive cells, and thus IL-6 might be taken into consideration as a possible therapeutic agent for preventing bone loss during periodontitis." (PMID 28497028, 2017). "In a study with postmenopausal Japanese women, it was revealed that IL-6 -572 G/C polymorphism may have an association between periodontitis and low truncal bone mineral density." (PMID 28624837, 2017). "MAPKs are intracellular enzymes that are involved in the response of cells to stimuli such as inflammatory cytokines.The pro-inflammatory cytokines, such as IL-1 and IL-6, TNFs, have been implicated in the stimulation of osteoclastic resorption in periodontitis." (PMID 27058519, 2016). "IL-6 is responsible for modulating the inflammatory cascade associated with chronic periodontitis." (PMID 27834922, 2016).
periodontitis (continued). "The inflammation reduction in the AAV-sh-Atp6v1c1 treatment group may be due to the down regulation of IL-6 (a pro-inflammatory cytokine associated with periodontitis)." (PMID 26274612, 2015). "However, an association was found between IL-6 −174 and aggressive periodontitis in a separate meta-analysis." (PMID 24551049, 2014). "Therefore, the aim of the present study was to investigate the association between IL6 c.-174G>C gene polymorphism and periodontitis in a sample from Bahia, Brazil." (PMID 25548674, 2014). "Our results indicate an association between IL6 c.-174G>C polymorphism and periodontitis and showed that IL-6 may be considered as an important marker for periodontitis." (PMID 25548674, 2014). "Our data indicate an association between IL6 c.-174G>C polymorphism and periodontitis and showed that IL-6 may be considered an important marker for periodontitis." (PMID 25548674, 2014). "In conclusion, ovariectomy promotes alveolar bone resorption in rats with experimental periodontitis and the possible underlying mechanism may be due to the decreased IL-10 and increased IL-6, OPG, and RANKL in ovariectomized periodontal tissues." (PMID 24683547, 2014). "IL-6 has also been implicated to have a role on the pathogenesis of periodontitis." (PMID 23091492, 2012). "IL-6 is elevated in sites of refractory periodontitis compared to sites of stable, advanced periodontitis, which suggests that it could be a diagnostic marker for sites of active periodontal disease." (PMID 20407653, 2009). "Notably, the regulatory mechanisms between IL-6 and miR-181a-5p in BMMSCs underlying periodontitis are still unknown." (PMID 42275747, 2026). "Furthermore, inhibition of histones, a major component of NETs, substantially reduces upregulation of IL‐17‐related genes (IL‐17a, S100a9, and IL‐6), decreases IL‐17‐positive cells and Th17 cells accumulation, and subsequently protects against periodontal bone loss in periodontitis." (PMID 41031144, 2025). "In periodontitis, IL-6 is also an overexpressed cytokine, which is associated with tissue damage, as patients with periodontitis have been reported to have significantly higher levels of IL-6 in saliva and serum, associated with periodontitis severity and tooth loss." (PMID 41009326, 2025). "Periodontitis, mainly in moderate or severe levels, causes a more extensive systemic inflammatory response, thereby promoting dysfunction in the vascular endothelium, with high serum levels of IL-6, PTX3, sTWEAK, and Aβ1-40 associated with a poor prognosis in patients with lacunar, infarcts." (PMID 40231146, 2025). "This study aimed to compare salivary IL-6 and irisin levels between periodontally healthy individuals and those with Stage 3 Grade C periodontitis, assess their diagnostic accuracy, and explore their molecular involvement in periodontitis through in silico analyses." (PMID 41007333, 2025). "On the other hand, the inverse correlation between miRNA-200c-3p/miRNA-421-5p and ACE2 may indicate that the low levels of either miRNA tested did not inhibit the expression of ACE2, which we observed in severe periodontitis has a strong association with the upregulation of IL-6." (PMID 39917640, 2024). "Indeed, orthodontic forces may increase periodontal tissue and especially bone loss at periodontitis sites by further upregulating Interleukin (IL)-6, which is already elevated by bacterially induced periodontal inflammation." (PMID 37174882, 2023). "However, various inflammatory mediators that participate in bone loss and collagen degradation in periodontitis; these include interleukin (IL) family such as IL-1, IL-6, tumor necrosis factor-α, matrix metalloproteinases, and granulocyte colony-stimulating factor (G-CSF)." (PMID 37365568, 2023). "Moreover, higher CRP and IL-6 levels may be found in patients affected by periodontitis and an association between IL-6 levels, and the extent of periodontitis has been demonstrated." (PMID 35996409, 2022).
periodontitis (continued). "Furthermore, it has been reported that fibroblasts in gingival connective tissue produce IL-6 in response to calprotectin and may cause the progression of periodontitis via crosstalk between fibroblasts and macrophages." (PMID 34832662, 2021). "Systemic inflammatory disease states associated with periodontal disease are hypothesized to occur due to transmigration of periodontal pathogens and/or periodontitis-associated inflammatory mediators, such as IL-1, IL-6, CRP, and fibrinogen in the bloodstream." (PMID 34950607, 2021). "In the second protocol, the mice with Periodontitis showed decreased cardiac output (10 ± 0.8 vs. 15 ± 1.4 mL/min in Sham) and ejection fraction (37 ± 3 vs. 47 ± 2% in Sham) associated with increased myocardial cytokines (Interleukin-17, Interleukin-6, and Interleukin-4)." (PMID 32327711, 2020). "Periodontitis is one of the most common chronic infectious diseases and is caused mainly by gram-negative microaerophilic and anaerobic bacteria that colonize the subgingival area and produce significant amounts of proinflammatory mediators, mainly IL-1β, IL-6, PGE2, and TNF-α." (PMID 28243243, 2017). "Individual variations in the blood levels of IL-6 may modulate the predisposition to a number of inflammatory diseases, such as periodontitis, because it is a proinflammatory mediator that activates host cells and may in turn lead to extracellular matrix destruction." (PMID 25548674, 2014). "zeae N165 cells significantly reduced alveolar bone resorption, TNF-α, and IL-6 levels in rats with periodontitis, maintained a healthy oral and intestinal microbial community structure, and regulated the dominant species to alleviate periodontitis." (PMID 41635731, 2026). "confirm that MCP‐1 and TNF‐α levels are higher in sera from periodontitis patients than in healthy controls, differences of IL‐6 levels differed among studies." (PMID 41580300, 2026). "Elevated systemic markers, such as C-reactive protein (CRP) and interleukin-6 (IL-6), are frequently observed in both periodontitis and these comorbidities, indicating a convergence of pathological pathways." (PMID 41590813, 2026). "Studies of neutrophils isolated from patients with chronic periodontitis report increased secretion of pro-inflammatory cytokines, i.e., IL-8, IL-6, TNF-α, and IL-1β." (PMID 39936030, 2025). "In periodontitis, the immune system overreacts, producing too many inflammatory signals, such as interleukin-6 (IL-6), interleukin-1beta (IL-1β), and tumor necrosis factor-alpha (TNF-α)." (PMID 41333792, 2025). "Clinical studies indicate that serum leptin levels in periodontitis patients positively correlate with inflammatory markers like IL-6 and TNF-α." (PMID 41246338, 2025). "Il-1β, Il-6, and Tnf-α levels were increased significantly in the gingiva and cortex in periodontitis mice, which was similar to the results of previous studies." (PMID 40552124, 2025). "For example, polymorphisms in CDKN2A/B, Peroxisome Proliferator-Activated Receptor Gamma (PPARG), and IL6 genes have been implicated in both DM and CVD risk and have also shown associations with severe periodontitis." (PMID 41007869, 2025). "Elevated levels of inflammatory cytokines, such as TNF-α, IL-6, and IL-17, are common to both periodontitis and rheumatoid arthritis, contributing to systemic and local tissue destruction." (PMID 40703374, 2025). "Patients with periodontitis have been found to have elevated levels of IL-6 in gingival fluid and serum." (PMID 40282186, 2025). "IL-6 levels were significantly lower in the control group compared with all stages and grades of periodontitis at both assessment points (p < 0.05)." (PMID 41440349, 2025). "IL-6 participates in the pathogenesis of periodontitis through immune regulation as an important pro-inflammatory or by upregulating RANKL expression in osteoblasts to promote osteoclast differentiation and bone resorption." (PMID 40649395, 2025).